EGFR (epidermal growth factor receptor)
Diseases named in the same sentence as EGFR in open-access papers (continued):
Sharing a sentence is not in itself a finding about the gene and the disease.
glioma (continued). "This fact, along with the observed limited clinical efficacy of EGFR-inhibitors (an intact EGFR signaling-axis is required for an EGFR inhibitor to block PI3-kinase activity in glioma) suggest the necessity of PI3-kinase inhibitor for the effective treatment of the disease." (PMID 25425962, 2014). "This miRNA involved in proliferation, self-renewal and tumor growth can modulate differentiation by targeting EGFR and PDGFRα and may be a candidate glioma tumor suppressor." (PMID 24709958, 2014). "EGF/EGFR signaling dysregulation often occurs in gliomas and plays a key role in gliomagenesis." (PMID 24740103, 2014). "Based on previous studies, we hypothesized that PTPRK may regulate growth, invasion and migratory phenotype of glioma cells through tyrosine dephosphorylation of β-catenin and receptor tyrosine kinases such as EGFR." (PMID 23696788, 2013). "EGFR drives the evolution of glioma malignancy through downstream signaling." (PMID 23251243, 2013). "To test whether miR-145 suppresses the expression of ADAM17 and EGFR at protein level in glioma, we performed Western blot analysis." (PMID 23076445, 2013). "So far, other EGFR antagonists have resulted in limited clinical activity in glioma patients." (PMID 23782513, 2013). "In the EGFR-expressing glioma cell line LN18, DTX1 over-expression increased EGFR protein levels." (PMID 23451269, 2013). "In addition, EGFR activation has been shown to be a significant indicator of glioma deterioration, as it is a vital marker of poorly-differentiated gliomas." (PMID 23946790, 2013). "As miR-146b inhibits EGFR expression and suppresses malignancy in glioma cells, we hypothesised that MSC exosomes containing miR-146b could have an anti-tumor effect in vivo." (PMID 26082317, 2013). "Aberrant overexpression of EGFR has been observed in glioma." (PMID 23776563, 2013). "The first concerns the challenges of validating a RNAi-mediated targeted therapy approach in orthotopic models of glioma and the second concerns the surprising results suggesting that shRNA-mediated silencing of both Rictor and EGFR resulted in a complete eradication of tumors." (PMID 23555046, 2013). "In high-grade gliomas, the identification of patients that could benefit from EGFR inhibitors remains a challenge, hindering the use of these agents." (PMID 23874590, 2013). "However, the two studies did each reveal that EGFR overexpression is significantly greater in high-grade gliomas than in low-grade tumors." (PMID 23946790, 2013). "Similarly, pharmacologic EGFR inhibition led to the Rho/ROCK-dependent formation of stress fibers with consequent decreased glioma cell invasion." (PMID 24109588, 2013). "In addition, sub-optimal dosing of TMZ cooperatively reduces cell growth in EGFR inhibited glioma cells with concomitant Rho/ROCK-dependent inhibition of glioma cell invasion." (PMID 24109588, 2013). "The overexpression of EGFR has been shown to promote glioma cell motility and invasion." (PMID 23894344, 2013). "Together, these results strongly indicate the anti-apoptotic effect of NOTCH3 in glioma may occur at least via modulation of EGFR." (PMID 24143218, 2013). "Immunohistochemical analysis using an anti-BSH monoclonal antibody revealed that BSH was delivered effectively into the cells but not into EGFR-deficient glioma or primary astrocytes." (PMID 23691498, 2013). "In addition, a mutant form of EGFR expressed in glioma cells, named de2-7EGFR/EGFRvIII, was shown to translocate to mitochondria in an Src-dependent manner and to be phosphorylated on Y845." (PMID 23702846, 2013). "Recently, miR-128 was also shown to target EGFR and PDGFRα in glioma stem cells." (PMID 23690991, 2013).
glioma (continued). "However, compared to the established close association between EGFR high expression and EGFR gene amplification and mutation, the regulation mechanism for PDGFRA expression in glioma cells is yet unclear." (PMID 23630597, 2013). "Following the prediction, we indeed experimentally confirmed that miR-219-5p could target EGFR by directly binding to the 3′-UTR and brought about the translational repression of EGFR transcript in glioma cell lines." (PMID 23690991, 2013). "Although it has been reported that Angptl4 transcription is regulated by the MAPK signal cascade, the involvement of Angptl4 transcription in EGFR signaling in glioma cells is largely unknown." (PMID 23617883, 2013). "To address this, we made use of U87 glioma parental cell line along with its two derivatives U87-wtEGFR (that stably overexpress 3′-UTR-less wild type EGFR) and U87-ΔEGFR (that stably overexpress 3′-UTR-less vIII variant of EGFR)." (PMID 23690991, 2013). "Amplification and/or mutation of the epidermal growth factor receptor (EGFR) gene were found in up to 60% of primary GBM cases and are believed to be associated with the development of the malignant phenotype of glioma cells, e.g., proliferation and invasiveness." (PMID 24202447, 2013). "The dependency of our predictor classification to commonly used grade II/III glioma prognostic factors (1p19q loss of heterozygosity, IDH1 gene mutation and EGFR gene amplification) was analyzed using the NL validation cohort for which these molecular data were available." (PMID 23805239, 2013). "Interestingly, an opposite effect of Fibulin-3 in glioma was also shown; overexpression of Fibulin-3 inhibited malignant glioma growth by suppressing EGFR-AKT signaling." (PMID 23936443, 2013). "EGFRvIII may also activate NF-kB through mTORC2: thus, this deletion, that occurs in the majority of GBMs with EGFR amplification, may also preserve the function of the EGFR-NF-kB axis in glioma perpetuation." (PMID 24330732, 2013). "In addition, miR-219-5p inhibited MAPK and PI3K pathways in glioma cell lines in concordance with its ability to target EGFR." (PMID 23690991, 2013). "The differences in results of in vivo imaging in NSCLC and in gliomas might be due to the different genetic alterations of EGFR observed in gliomas although a previous study suggested that U87 cells were very sensitive to the EGFR inhibitor." (PMID 27408849, 2013). "Furthermore, a telomerase activity-deficient form of telomerase reverse transcriptase (TERT) was shown to induce EGFR expression in glioma cells, in a process coupled with the acquisition of stem-like traits." (PMID 23355974, 2013). "Moreover, enriched boron or 10B conjugated with anti-EGFR antibodies by ZZ-His provides a selective delivery system into glioma cells, and this was confirmed by inductively coupled plasma-atomic emission spectrometry (ICP-AES) both in vitro and in vivo." (PMID 23691498, 2013). "This indicates that in addition to EGFR other tyrosine kinase receptors might be important for invasion and a mesenchymal phenotype in high-grade glioma." (PMID 23429996, 2013). "EphrinA5L acts as a tumor suppressor by negatively regulating EGFR expression in glioma." (PMID 22860012, 2012). "In addition, in glioma cells, miR-7 binds to the EGFR 3’UTR and decreases cell invasiveness by suppressing translation of EGFR." (PMID 22681957, 2012). "EGFR activation promotes migration of normal neuroblasts, astrocytes, and glioma cells." (PMID 22570591, 2012). "We performed Bonferroni correction in our statistical analysis and found no statistical significant associations between EGFR SNPs and glioma risk." (PMID 22662167, 2012). "Given the important roles of EGF in cell proliferation, differentiation or survival through binding to EGFR, it is biologically plausible that EGF polymorphism may modulate the risk of glioma." (PMID 22829952, 2012).
glioma (continued). "In addition, higher expression of EGFR in mammary, glioma, hepatocellular carcinoma and malignant epithelial nasal tumors of canine origin closely parallels that of human tumors of the same type and histologic grade." (PMID 22216938, 2012). "The detection of truncated isoforms, depending on the antibody used, could explain some of the discrepancies found in literature regarding EGFR expression in gliomas." (PMID 22159595, 2012). "Their findings, combined with our results, indicate that EGFR pathways may play a key role in the development of glioma." (PMID 22662167, 2012). "Recent evidence suggests that PDGF- and EGFR-induced gliomas may represent a distinct biology and cell of origin from other glioma subtypes." (PMID 21931722, 2011). "The PI3K/Akt signaling pathway can be upregulated in gliomas through several mechanisms, most commonly through mutation or loss of heterozygosity of PTEN or through amplification/over-expression of critical growth factor receptors such as EGFR and PDGFR." (PMID 21267448, 2011). "Concerning the epidermal growth factor receptor (also known as ErbB1 or HER1), is usually over-activated in most human tumors, and particularly in gliomas mostly due to gene amplification leading to a marked enhancement of cellular motility, invasion, and proliferation." (PMID 22091432, 2011). "The tumor-suppressive effect of EFEMP1 to glioma cells may also be applicable to other cancer types that have hyperactivation of EGFR and AKT signaling pathways." (PMID 21955618, 2011). "qPCR analysis of a panel of these and 15 other murine gliomas containing regions comprised of recruited cells was consistent with amplification of EGFR at the DNA level occurring at most in 6 of 18 (∼30%) of all cases, while IGFR was only amplified at most in 2 of 19 (∼10.5%)." (PMID 21754979, 2011). "In our opinion ACTB does not represent the best reference gene for normalization because it is located at 7p15-p12, a chromosomal site subject to copy number variations in gliomas, and because it is close EGFR (located at 7p12) that is amplified in about 40% of GBMs." (PMID 20167086, 2010). "For example, gliomas with similar EGFR gene copy number and mRNA over-expression may accumulate quite different levels of the corresponding protein." (PMID 21170331, 2010). "For example, epidermal growth factor (EGF) could be used to specifically target EGF receptor- (EGFR-) positive tumours (these include melanomas, gliomas, breast, prostate, and ovarian cancers)." (PMID 20871837, 2010). "Amplification of EGFR (or gain of chromosome 7) is often seen in high-grade gliomas." (PMID 20423517, 2010). "In this report we demonstrate that QDs specifically targeted to EGFR, can clearly distinguish low-grade as well as high-grade glioma tissue from normal brain tissue both at the macroscopic and the single cell level with very high contrast ratios in ex vivo experiments." (PMID 20614029, 2010). "These previous studies suggested that overexpression of EGF and EGFR might affect cell activities in brain tissues, abnormity of which may contribute to the glioma." (PMID 20487573, 2010). "The role of EGFR in glioma biology is well established (and references therein)." (PMID 20824129, 2010). "Indeed, EGFR is overexpressed in a variety of human cancers including lung, head and neck, colon, pancreas, breast, ovary, bladder and kidney, and gliomas." (PMID 21165163, 2010). "As an important receptor of EGF with high affinity, EGFR was often overexpressed in glioma cells." (PMID 20487573, 2010). "HER1/EGFR was found to be disregulated in various human cancers including high-grade glioma." (PMID 20657384, 2010). "In addition, we first showed the ability of mAb specifics against EGFR to target radioresistant glioma CSC, supporting the potential use in patients." (PMID 19293809, 2009).
glioma (continued). "Genetic analyses demonstrated that EGFR-Ras and PI3K induce fly glial neoplasia through activation of a combinatorial genetic network composed, in part, of other genetic pathways also commonly mutated in human glioma." (PMID 19214224, 2009). "The expression of EGFR was found in specimens from 2 of the 6 low-grade gliomas." (PMID 18398462, 2008). "Still using the most differentially expressed 1366 probe sets, the samples clustered into two major groups: one containing 1p19q codeleted gliomas, normal white matter and normal grey matter, and the other containing EGFR amplified gliomas and cancer stem cells." (PMID 18492260, 2008). "To validate these findings, we studied the expression of 22 selected genes differentially expressed (11 up and 11 down) between the two groups of gliomas in an independent data set of 16 gliomas (8 gliomas with EGFR amplification and 8 gliomas with 1p19q codeletion)." (PMID 18492260, 2008). "In addition, EGFR over-expression was detected in 11 of the 17 high-grade glioma specimens analyzed." (PMID 18398462, 2008). "To determine whether doxycycline can block MMP activity, we measured the extent of doxycyline-mediated MMP-2 and MMP-9 inhibition in vitro using epidermal growth factor receptor (EGFR) transfected U251 glioma cell lines." (PMID 18186943, 2008). "EGFR is also frequently overexpressed in high-grade glioma cells." (PMID 18398462, 2008). "In this study we determined whether or not doxycycline could block MMP-2 and MMP-9 activities, by measurements of doxycyline-mediated MMP-2 and MMP-9 inhibition in vitro using epidermal growth factor receptor (EGFR) transfected U251 glioma cell lines." (PMID 18186943, 2008). "Moreover, response of xenografted gliomas to different alkylating agents was attenuated by EGFR amplification." (PMID 17342095, 2007). "Similar 3′ deletions in EGFR have been observed previously in gliomas." (PMID 18688287, 2007). "In addition, we establish an association between nuclear FABP7 and EGFR expression both in human GBM tumors and in a glioma cell line." (PMID 16623952, 2006). "Further characterisation revealed that mAb 806 could recognise cell lines and glioma specimens when the wt EGFR was overexpressed, especially when the EGFR gene was amplified, but not normal tissue." (PMID 15770208, 2005). "The absence of H3K27 mutations and the presence of EGFR mutations in bithalamic high-grade gliomas suggest that they may be a distinct entity." (PMID 41596345, 2026). "However, whether scutellarin and even its combination with lidocaine exert anti-glioma effect by regulating EGFR signaling remains to be established." (PMID 39888904, 2025). "Interestingly, 3 out of 13 gliomas did not present mutations in IDH, TERT, or EGFR, and were thus classified as “Diffuse gliomas IDH-wild type NEC (Not Elsewhere Classified)”." (PMID 41567539, 2025). "Furthermore, the PI3K-AKT-dependent actions on motility may represent a generalized pathway in cancers with FAT1 overexpression, for example, as reported in high-grade gliomas whose invasiveness was dependent upon EGFR-AKT signaling." (PMID 40083689, 2025). "Therefore, we speculated that SCU and even its combination with lidocaine might exert the anti-glioma effect by regulating EGFR signaling." (PMID 39888904, 2025). "Additionally, FPR1 may contribute to gliomas and neuroblastoma progression by transactivation of the epidermal growth factor receptor (EGFR)." (PMID 41283264, 2025). "Also, DWI/ADC may support the identification of EGFR amplification since EGFR-amplified gliomas show lower mean ADC values as compared to EGFR-wild-type gliomas." (PMID 40870498, 2025). "In the absence of EGFR mutations, increased levels of its ligands are often observed, which activates the receptor in an autocrine manner, resulting in autonomous growth of glioma cells." (PMID 40428422, 2025).
glioma (continued). "Emerging evidence suggests that TGF-α/EGFR signaling plays a pivotal role in tumor cell proliferation, differentiation, and survival, raising the possibility that TGFA itself may represent a novel glioma susceptibility locus and therapeutic target." (PMID 41267963, 2025). "Therefore, sequencing of the Ras gene should be performed when analyzing EGFR-related mechanisms in gliomas to rule out confounding effects from Ras mutations." (PMID 40723354, 2025). "Thus, further investigation into the relationship between cuproptosis and EGFR may shed new light on the application of EGFR inhibitors in gliomas." (PMID 38956740, 2024). "Importantly in our study, EGFR mutation was absent in LGGs from the neocortex, and the mutation rate was significantly lower than that in mesocortex LGGs, suggesting EGFR amplification in the mesocortex gliomas may be a potential predictor for survival." (PMID 37588233, 2024). "However, the mechanism by which WZ-3146 acts as an EGFR inhibitor to inhibit KIF4A expression in glioma remains unclear." (PMID 38937742, 2024). "Some molecular markers, such as IDH, 1p/19q codeletion, EGFR amplification, CDKN2A/B loss, and TERT promoter mutation, etc. have been routinely tested in clinical practice and cooperated with histopathological information to form the classification scheme of glioma." (PMID 39906742, 2024). "It was shown that miR-375 might be able to inhibit glioma growth by repressing the Cellular Communication Network factor 2 (CCN2 or CTGF)-epidermal growth factor receptor signaling pathway, resulting in the reduction of glioma proliferation, migration and invasion." (PMID 39684236, 2024). "However, it has been indicated that poor prognosis low-grade gliomas (G2 grade) without IDH mutation are characterized by EGFR amplification." (PMID 38254732, 2024). "Additionally, EGFR signaling regulates the proliferation, differentiation, and maturation of astrocytes, which is important for understanding gliomagenesis, as astrocytes can act as cells of origin for gliomas." (PMID 39722126, 2024). "Moreover, data suggests that EGFR amplification is evident in high-grade gliomas (25%)." (PMID 38893240, 2024). "Furthermore, EGFR signaling has the ability to enhance glutamate release from glioma cells." (PMID 37241023, 2023). "Moreover, despite the absence of histological features of high‐grade malignancy (necrosis, angiogenesis), an IDHwt glioma can still be classified as GBM when EGFR amplification, the combination of gain of chromosome 7 and loss of chromosome 10 (7+/10‐), and TERT promoter mutation are present." (PMID 36776000, 2023). "Meta-analyses of studies on gliomas (including all grades) have proposed that the expression of the EGFR protein and mutations in PTEN may have negative effects on overall survival, although their effects have not been evaluated individually in IDH1-W-GBs." (PMID 36831729, 2023). "Though around 50% patients harbored the EGFRνIII deletion, and EGFR amplification was maintained at the time of recurrence, neither EGFR inhibitors nor monoclonal antibodies targeting extracellular EGFR showed a survival benefit among recurrent-glioma patients." (PMID 37444531, 2023). "Thus, patients with high-risk scores may be well suited for a combination of immunotherapy and EGFR-targeted agents, which is currently rarely investigated in gliomas and deserves further exploration." (PMID 37759950, 2023).